SLC25A19 (solute carrier family 25 member 19)
Description:
Mitochondrial transporter mediating uptake of thiamine diphosphate into mitochondria. It is not clear if the antiporter activity is affected by the membrane potential or by the proton electrochemical gradient.
Synonyms: MTPPT; DNC; MUP1; TPC; MCPHA; THMD3; THMD4
Tractability: Antibody: UniProt predicts a signal peptide or a membrane-spanning region. PROTAC: ubiquitination databases record sites on it; its protein half-life has been measured.
Gene: Protein-coding gene on chromosome 17 (75,272,012 to 75,289,968, reverse strand). Ensembl gene ENSG00000125454.
Subcellular location: Mitochondrion membrane
Subcellular location (Human Protein Atlas): Mitochondria
Pathways (Reactome):
Metabolism: Vitamin B1 (thiamin) metabolism
Gene Ontology:
Molecular function: deoxynucleotide transmembrane transporter activity; thiamine pyrophosphate transmembrane transporter activity; nucleobase-containing compound transmembrane transporter activity
Biological process: deoxynucleotide transport; thiamine pyrophosphate transmembrane transport; thiamine-containing compound metabolic process; thiamine diphosphate biosynthetic process; transmembrane transport
Cellular component: mitochondrial membrane; mitochondrion; nucleus; mitochondrial inner membrane
Genetic constraint (gnomAD): Loss-of-function variants: 19 observed, 28.27 expected, observed/expected ratio (o/e) 0.67, 90% interval 0.47 to 0.99. The upper end of that interval is the gene's LOEUF score, 0.99, which puts it in group 4 of 6, group 1 being the genes least tolerant of losing a copy. Missense variants: 319 observed, 379.33 expected, observed/expected ratio (o/e) 0.84, 90% interval 0.77 to 0.92. Synonymous variants: 153 observed, 153.58 expected, observed/expected ratio (o/e) 1, 90% interval 0.87 to 1.14.
Gene-disease validity (ClinGen):
ClinGen rates the evidence that SLC25A19 causes each of these diseases.
Leigh syndrome (autosomal recessive): Limited. A progressive neurological disease defined by specific neuropathological features associating brainstem and basal ganglia lesions.
Homologues: Orthologues: chimpanzee SLC25A19 (99% identical), macaque SLC25A19 (97% identical), dog SLC25A19 (81% identical), guinea pig SLC25A19 (80% identical), pig SLC25A19 (79% identical), mouse Slc25a19 (75% identical), rat Slc25a19 (73% identical), tropical clawed frog slc25a19 (65% identical), zebrafish slc25a19 (60% identical), Caenorhabditis elegans hpo-12 (39% identical), Drosophila melanogaster Tpc1 (36% identical), Drosophila melanogaster Tpc2 (32% identical). Paralogues in human: SLC25A12 (27% identical), SLC25A13 (26% identical), SLC25A16 (25% identical), SLC25A24 (25% identical), SLC25A48 (25% identical), SLC25A21 (24% identical), SLC25A25 (24% identical), SLC25A28 (24% identical), SLC25A29 (24% identical), SLC25A37 (24% identical), SLC25A39 (24% identical), SLC25A45 (23% identical), and 37 more.
Diseases named in the same sentence as SLC25A19 in open-access papers:
SLC25A19 is named in the same sentence as 39 diseases in open-access papers, as found by Europe PMC text mining. Sharing a sentence is not in itself a finding about the gene and the disease. The quoted sentences say what the papers report.
microcephaly (10 papers, 2011 to 2025). A congenital or acquired developmental disorder in which the circumference of the head is smaller than normal for the person's age and sex. "A mutation in the Slc25a19 gene was found to be associated with Amish microcephaly, neuropathy and bilateral striatal necrosis." (PMID 30537945, 2018). "The SLC25A19 gene is clinically important as mutations in this gene cause Amish congenital lethal microcephaly (an autosomal recessive disorder associated with retardation in brain development), and neuropathy and bilateral striatal necrosis." (PMID 24023687, 2013). "For example, Amish lethal microcephaly is caused by a mutation of the SLC25A19 (Solute carrier family 25 member 19), coding for a mitochondrial thiamine pyrophosphate carrier, which is a coenzyme for α-ketoglutarate dehydrogenase that operates in the TCA (tricarboxylic acid) cycle." (PMID 35069108, 2021). "Moreover, a point mutation in a conserved residue in SLC25A19 that affects its transporter function, has been identified in congenital microcephaly, a severe form of encephalopathy with brain malformations." (PMID 28706281, 2017). "The Amish lethal microcephaly (MCPHA; OMIM 607196), also known as thiamine metabolism dysfunction syndrome-3 (THMD3), is caused by homozygous mutation in the SLC25A19 gene." (PMID 31019473, 2019).
breast carcinoma (4 papers, 2013 to 2022). "A recent report showed that SLC25A19 is up-regulated in 43 breast cancer specimens, indicating its roles in breast cancer." (PMID 35371321, 2022). "TPK1, SLC19A2/THTR1 and SLC25A19/TPC have been shown to be up-regulated in breast cancer in both patients and cell lines." (PMID 25788274, 2015). "Recently, our group discovered a significant increase in the gene expression of TPK1, SLC19A2, and SLC25A19 in breast cancer tissue samples compared to normal breast tissue." (PMID 24280319, 2013). "Upregulation of TPK-1, SLC19A2, SLC25A19 and downregulation of SLC19A3 was also verified in several breast cancer cell lines compared to human mammary epithelial cells (hMECs)." (PMID 24280319, 2013).
Amish lethal microcephaly (3 papers, 2019 to 2024). Amish lethal microcephaly is a very rare syndrome characterized by extreme microcephaly and early death, within the first year. "Mutations in SLC25A19 are associated with Amish lethal microcephaly (MCPHA), a condition characterised by severely impaired brain development and α-ketoglutaric aciduria." (PMID 39313811, 2024). "In more detail, these mutants presented not only metabolic alterations but also central nervous system defects, which were similar to those observed in patients affected by Amish lethal microcephaly (MCPHA), a syndrome associated with a SLC25A19 loss-of-function mutation." (PMID 32842667, 2020).
progressive polyneuropathy (3 papers, 2019 to 2024). "For instance, SLC25A19 deficiency might result in bilateral striatal degeneration and progressive polyneuropathy." (PMID 39344563, 2024).
prostate carcinoma (3 papers, 2016 to 2024). A carcinoma that arises from epithelial cells of the prostate gland. "In prostate cancer, the decreased expression of SLC25A19 plays a role in regulating the tricarboxylic acid cycle metabolism by restricting the availability of the cofactor thiamine pyrophosphate." (PMID 39344563, 2024).
bladder cancer (2 papers, 2022 to 2024). "In addition to discovering that the AKT/mTOR pathway is involved in regulating the progression of bladder cancer, we also identified downstream target proteins (c-Myc, SLC25A19, and ICAM5) of UCHL5 by RNA-Seq." (PMID 36428630, 2022). "According to RNA-Seq analyses and Western blotting experiments, the expression of c-Myc, SLC25A19, and ICAM5 was modified as a result of UCHL5 activating AKT/mTOR signaling in bladder cancer cells." (PMID 36428630, 2022). "All things considered, our findings show that increased UCHL5 expression stimulates AKT/mTOR signaling, subsequently triggering the expression of c-Myc, SLC25A19, and ICAM5, which in turn promotes carcinogenesis in bladder cancer." (PMID 36428630, 2022). "Finally, bladder cancers with knockdown or overexpression of UCHL5 were treated with either SC79 or LY294002 to examine the participation of the AKT/mTOR signaling pathway and the expression of downstream targets c-Myc, SLC25A19, and ICAM5." (PMID 36428630, 2022).
Leigh syndrome (2 papers, 2017 to 2020). "Furthermore, mutations in thiamine metabolism genes SLC19A3, SLC25A19 and TPK15, 7, 12, 13 have been reported to result in Leigh syndrome, a progressive neurodegenerative disorder of early childhood." (PMID 28706281, 2017).
colorectal cancer (1 paper, 2024). A primary or metastatic malignant neoplasm that affects the colon or rectum. "Relationship between SLC25A19 expression and tumor characteristics in patients with colorectal cancer." (PMID 39344563, 2024).
gastric cancer (1 paper, 2022). A primary or metastatic malignant neoplasm involving the stomach. "No recurrent MET fusions were identified, some of the fusion partners included HLA-DRB1-MET (lung cancer), CD47 (lung cancer), CAPZA2 (gastric cancer), AKAP9 (hepatobiliary cancer), CLIP2 (hepatobiliary cancer), and SLC25A19 (ovarian cancer)." (PMID 36369474, 2022).
metabolism (1 paper, 2021). "Thiamine metabolism dysfunction syndrome 4 (THMD4, OMIM #613710) is an autosomal recessive inherited disease caused by the deficiency of SLC25A19 that encodes the mitochondrial thiamine pyrophosphate (TPP) transporter." (PMID 34587972, 2021).
cancer (5 papers, 2021 to 2024). A tumor composed of atypical neoplastic, often pleomorphic cells that invade other tissues. "Research has implicated SLC25A19 in the progression of various diseases, including mitochondrial diseases, neurological disorders, and cancer." (PMID 39344563, 2024). "In this study, SLC25A19 knockdown produced strong inhibitory effects on cancer‐related phenotypes and tumor growth, highlighting SLC25A19's importance in CRC progression." (PMID 39344563, 2024). "On the other hand, SLC7A6 and SLC25A19 play crucial roles in cancer by affecting amino acid transport, energy metabolism, and potential therapeutic targets." (PMID 37737478, 2023). "The expression of SLC25A19 was stronger in CRC tissues than in para‐carcinoma tissues." (PMID 39344563, 2024). "The objective of this study was to explore the involvement of SLC25A19 in CRC and its mechanism in regulating of cancer progression." (PMID 39344563, 2024). "To clarify the molecular mechanisms by which SLC25A19 regulates CRC progression, we examined the phosphorylation level of key proteins in cancer‐related pathways by using the human phospho‐kinase array." (PMID 39344563, 2024). "Nevertheless, the biological roles of SLC25A19 in cancer cellular properties and tumor growth have not been reported thus far." (PMID 39344563, 2024). "Additionally, the expression of SLC25A19 was validated in CRC tissues and para‐carcinoma tissues through IHC staining using a human tissue array." (PMID 39344563, 2024).
tumor (3 papers, 2009 to 2025). "Subsequently, a xenograft tumor model was constructed to validate the inhibitory effects of SLC25A19 knockdown." (PMID 39344563, 2024). "Subsequently, the xenograft tumor model was constructed to evaluate the effect of SLC25A19 on tumor growth in vivo." (PMID 39344563, 2024). "Next, we established mouse xenograft models to assess the impact of SLC25A19 on CRC tumor growth in vivo by subcutaneously injecting RKO cells transfected with shCtrl or shSLC25A19 into nude mice." (PMID 39344563, 2024). "Solute carrier family 25 member 19 (SLC25A19) is a member of the solute carrier family that contribute to cellular functions, including tumor biology." (PMID 39344563, 2024). "Consistent with the in vitro proliferation assay, the tumors from the shSLC25A19 group contained fewer Ki‐67‐positive cells than those from the shCtrl group, confirming that SLC25A19 may contribute to tumor proliferation in vivo." (PMID 39344563, 2024). "It showed that downregulated SLC25A19 could delay tumor formation and retard tumor growth." (PMID 39344563, 2024). "Functional analysis revealed that knockdown of SLC25A19 effectively suppressed CRC cell proliferation and migration, induced apoptosis in vitro, and attenuated tumor growth in vivo." (PMID 39344563, 2024). "In our study, we delved into the investigation of SLC25A19 expression in CRC and its potential impact on tumor progression." (PMID 39344563, 2024). "Upon analyzing the protein expression of SLC25A19 in CRC tumor tissues and adjacent noncancerous tissues, we observed a significant upregulation of SLC25A19 in CRC." (PMID 39344563, 2024).
metabolic disease (2 papers, 2018 to 2020). A congenital disorder (due to inherited enzyme abnormality) or acquired (due to failure of a metabolically important organ) disorder resulting from an abnormal metabolic process. "SLC25A19 defect: Thiamine metabolism dysfunction syndrome-4 (THMD4) represents an autosomal recessive ultrarare metabolic disorder characterized by childhood onset of episodic encephalopathy, often associated with a febrile illness, and causing transient neurologic dysfunction." (PMID 32933220, 2020).
SLC25A19 also shares sentences with these, for which no sentence is quoted: Obesity (15 papers); Insulin resistance (6); Glucose intolerance (4); diabetes (3); Encephalopathy (3); Hyperglycemia (3); neuropathy (3); type 2 diabetes (3); polyneuropathy (2); Roger’s syndrome (2); atherosclerosis (1); Charcot-Marie-Tooth disease (1); colon adenocarcinoma (1); diabetic nephropathy (1); generalized dystonia (1); Hepatic steatosis (1); hydronephrosis (1); Hyperinsulinemia (1); infection (1); lentivirus infection (1); lung carcinoma (1); megaloblastic anemia (1); mitochondrial disease (1); neurological disorders (1); ovarian carcinoma (1); type 1 diabetes mellitus (1).